TLR2 (toll like receptor 2)
Diseases named in the same sentence as TLR2 in open-access papers (continued):
Sharing a sentence is not in itself a finding about the gene and the disease.
Parkinson disease (40 papers, 2014 to 2025). A progressive degenerative disorder of the central nervous system characterized by loss of dopamine producing neurons in the substantia nigra and the presence of Lewy bodies in the substantia nigra and locus coeruleus. "New results confirmed that phosphorylated α-synuclein presence in vagus nerve SCs caused activation of the TLR2/MyD88/NF-κB signaling pathway, leading to neuroinflammatory responses and Parkinson’s disease autonomic dysfunction." (PMID 40940747, 2025). "The TLR2-mediated cell response is also implicated in Parkinson’s disease (PD), another age-related neurodegenerative disorder." (PMID 38299364, 2024). "Research on Parkinson’s disease models has revealed that mice deficient in the TLR2 gene had reduced accumulation of α-synuclein and enhanced motor deficits." (PMID 39006715, 2024). "There is evidence that suggests that the TLR2/TLR10 heterodimer mediates the proinflammatory response triggered by the binding of TLR2 to PAMPs of Listeria monocytogenes, Helicobacter pylori bacteria, influenza A virus, and molecular patterns associated with Parkinson’s disease." (PMID 39457048, 2024). "Researchers found that TLR2 could contribute to disease advancement by preventing autophagy and promoting the accumulation of α-syn, a protein linked to the formation of Lewy bodies, a characteristic symptom of Parkinson’s disease." (PMID 39006715, 2024). "However, targeting Toll-like receptor 2 and Toll-like receptor 4 may have diagnostic potential to predict patients at risk of Parkinson’s disease or to stratify disease progression." (PMID 37207228, 2023). "Therefore, Toll-like receptor 2 and Toll-like receptor 4 are potential targets to develop new therapies to alter the course of disease in people at high risk of Parkinson’s disease and improve gut disorders in patients in the prodromal phase or with established disease." (PMID 37207228, 2023). "Thus, early gut dysfunction signaling pathways caused by Toll-like receptor 2 and Toll-like receptor 4 destructions may directly lead to elevated α-synuclein levels and aggregation in prodromal Parkinson’s diseases." (PMID 37207228, 2023). "In pathological conditions, amyloid-β (Aβ) and tau (key players in Alzheimer’s’ disease (AD)) induce TLR4 activation, while α-synuclein (a key player in Parkinson’s disease (PD)) induces TLR2 and TLR5 activation." (PMID 41280719, 2025). "A recent research report indicated that TLR10 regulates TLR2-induced cytokine production in monocytes isolated from Parkinson’s disease patients." (PMID 37569837, 2023). "We reviewed the latest evidence that disrupted Toll-like receptor 2 or Toll-like receptor 4 signaling pathway leads to Parkinson’s disease in gut homeostasis and enteric nervous system, as well as gut dysfunction in Parkinson’s disease." (PMID 37207228, 2023). "TLR10 on peripheral blood monocytes reduces TLR2-induced cytokine production in Parkinson’s disease, which is also a co-receptor of TLR2." (PMID 35126357, 2021). "Beneficial effects of targeting TLR2 have also been described in animal models of other neurodegenerative pathologies of the CNS, including Alzheimer’s and Parkinson’s diseases." (PMID 34360582, 2021). "Clinical studies have shown that TLR2 is overexpressed in the microglia of patients with Parkinson’s disease (PD), especially in the substantia nigra and the hippocampus region of the brain in the early stages of the disease." (PMID 34827372, 2021). "It was also demonstrated that TLR2 is expressed in CNS neurons, and its levels increase in the Parkinson disease brain." (PMID 34552146, 2021). "There is increasing evidence of an involvement of TLRs, especially TLR2, 4 and 9 in neurodegenerative diseases such as Alzheimer’s disease (AD), Parkinson’s disease (PD), and amyotrophic lateral sclerosis (ALS)." (PMID 30333729, 2018). "Notably, Tlr2 has been shown in Parkinson’s disease to promote prion-like propagation of protein aggregates through microglial activation." (PMID 41354822, 2025).
Parkinson disease (continued). "TLR2 has been shown to have a role in the onset and progression of Parkinson’s disease." (PMID 39006715, 2024). "Similarly, in Parkinson’s disease, the accumulation of α-synuclein aggregates triggers microglia via TLR2 signaling, amplifying inflammatory responses, while dysfunction in gut–brain axis interactions suggests systemic contributions to CNS pathology." (PMID 39769374, 2024). "Notably, Toll-like receptor 2 is colocalized with α-synuclein in the anterior cingulate cortex of postmortem brain tissue in Parkinson’s disease patients." (PMID 37207228, 2023). "Therefore, further investigation of Toll-like receptor 2/4-mediated gut dysfunction for Parkinson’s pathogenesis and pathology is urgently needed." (PMID 37207228, 2023). "We suspect that Toll-like receptor 2 and Toll-like receptor 4 signaling pathways may promote Parkinson’s disease pathogenesis by increasing gut permeability and gut inflammation, thereby driving α-synuclein aggregation in the gut or brain." (PMID 37207228, 2023). "Overall, these results suggest that enteroendocrine cells could be a site of α-synuclein accumulation in Parkinson’s disease when stimulated by specific bacterial ligands through TLR2/4 activation and butyrate acting on FFA2/3." (PMID 37953845, 2023). "Thus, it has consistently been suggested that elevated neuronal Toll-like receptor 2 levels are a consequence of the disease process in Parkinson’s disease patients." (PMID 37207228, 2023). "Toll-like receptor 2 expression is increased in monocytes in Parkinson’s disease patients." (PMID 37207228, 2023). "Given its established role in innate immunity, Toll-like receptor 2 may play a key role in microbiome-induced systemic action, and there are several pieces of evidence that the Toll-like receptor 2 signaling pathway is altered in Parkinson’s disease patients." (PMID 37207228, 2023). "While Toll-like receptor 2 and Toll-like receptor 4 in Toll-like receptors are important sub-receptors for inducing Parkinson’s disease development, Toll-like receptor 2 and Toll-like receptor 4 are generally expressed in a healthy gut but are more obvious in the colon." (PMID 37207228, 2023). "In addition, TLR2 plays an important role in the pathogenesis of neurodegenerative diseases such as Alzheimer’s disease (AD) and Parkinson’s disease (PD)." (PMID 35396576, 2022). "Neurons, microglial cells and macrophages, for example, are also known to express TLR receptors (especially TLR2, 4 and 9) and these receptors are overexpressed in patients with Alzheimer’s or Parkinson’s diseases, and in various experimental models of these diseases." (PMID 33918172, 2021). "Previous studies have found that TLR2 is involved in microglial activation in a variety of neurological diseases and psychiatric disorders, such as Parkinson’s disease, spinal cord injury, Alzheimer’s disease, multiple sclerosis, and repeated social defeat stress." (PMID 32393298, 2020). "However, targeting Toll-like receptor 2 and Toll-like receptor 4 in the gut may exert multiple benefits when administered alone or in combination with current Parkinson’s disease therapies." (PMID 37207228, 2023). "Similarly, considering Parkinson’s disease pathology, Toll-like receptor 2/4 in the gut is targeted to mitigate α-synuclein aggregation and pathological changes by modifying the gut–brain axis diffusion pattern through lifestyle interventions, probiotics, or specific therapies." (PMID 37207228, 2023). "Notably, Toll-like receptor 2 and Toll-like receptor 4 are dysregulated in Parkinson’s disease patients and may therefore be identified as the core of early gut dysfunction in Parkinson’s disease." (PMID 37207228, 2023). "Indeed, neuroinflammation can be elicited through the TLR2-mediated pathway either by endogenous molecules such as α-synuclein and amyloid β-peptide in Parkinson and Alzheimer disorders respectively or by infectious insult as previously demonstrated for herpes simplex virus type 1." (PMID 25790282, 2015).
Parkinson disease (continued). "Upregulation of TLRs expression was observed in a variety of chronic neurodegenerative diseases, such as Alzheimer’s disease (TLR2 and TLR4), multiple sclerosis (TLR 1-8), and Parkinson’s disease (TLR2 and TLR5)." (PMID 35740099, 2022). "The role of Toll-like receptor 2 (TLR2) in the central nervous system (CNS) is critical in several conditions including neurological disorders such as pain, and neurodegenerative disorders such as Parkinson’s disease." (PMID 41296096, 2025). "Intestinal microbiota and Toll-like receptor 2 (TLR2), which can bind lipoteichoic acid produced by microbiota, might contribute to the pathogenesis of Parkinson’s disease (PD), which is characterized by α-synuclein accumulation." (PMID 38257933, 2024). "Therefore, Toll-like receptor 2 and Toll-like receptor 4 are likely to affect candidates for leaky gut and inflammatory responses, intestinal denervation, and early colonic motility disorders, all of which may help explore the pathogenesis of Parkinson’s disease." (PMID 37207228, 2023). "Additionally, there is evidence that TLR2 and TLR4 play a role in Parkinson ́s disease through microglia activation." (PMID 33499143, 2021). "More importantly, expression levels for TLR2, TLR5, and CD14 are increased in Parkinson’s disease." (PMID 25586882, 2015). "For instance, extracellular α-syn oligomers and fibrils produced during the course of Parkinson disease (PD) bind to TLR4 and TLR2 expressed on microglia." (PMID 35563729, 2022).
allergic disease (39 papers, 2005 to 2025). An immune response that occurs following re-exposure to an innocuous antigen, and that requires the presence of existing antibodies against that antigen. "For example, single nucleotide polymorphisms (SNPs) in CD14, TLR4, and TLR2 genes have been correlated with the development of allergy sensitization and symptoms of allergy in children." (PMID 36704753, 2022). "This phenomenon requires attention in future studies, as TLR2 was also associated with allergic diseases." (PMID 35386993, 2021). "TLR2 polymorphisms have been investigated in the field of atopy and allergic diseases, involving AD, but the results of published association studies on TLR2 SNPs and the risk of AD are contradictory." (PMID 28443596, 2017). "One is located near the toll like receptor 6 (TLR6) gene, which functionally interacts with toll-like receptor 2, and is associated with an increased risk of other allergic diseases." (PMID 26941931, 2015). "In the children with allergy high expression of TLR2+ on pDCs was strongly associated with a distinct innate immune response and allergic disease phenotype." (PMID 22295096, 2012). "Understanding the regulation of SPLUNC1 by TLR2 signaling will help design novel therapeutic approaches to restore SPLUNC1 levels in hosts with allergic diseases and cigarette smoke-associated diseases (e.g., COPD) which exhibit impaired SPLUNC1 production." (PMID 21054862, 2010). "Familial allergy risk (maternal allergy) has also been associated with reduced neonatal TLR2 responses (p = 0.03; n = 9), and lower TLR2, TLR4, and CD14 messenger RNA levels in cord blood (n = 185)." (PMID 23283295, 2008). "TLR2 is related to protection against allergies and allergic asthma by sensing pathogen associated patterns as lipoproteins and lipopeptides." (PMID 18315836, 2008). "Notably, higher cytokine production upon TLR2 stimulation was linked to a lower prevalence of allergy (MR P = 3.48 × 10−20)." (PMID 38714679, 2024). "Second, in terms of the development of allergic disease, both TLR2 and TLR4 exhibit polymorphisms in their genes that may alter the protective effect of microbial exposure as proposed in the hygiene hypothesis." (PMID 19662206, 2007). "In the farming group, through the TLR2/4 pathway, maternal microbial over-load affected the quantity and function of neonatal Tregs, which regulated the early differentiation of Th1/Th2, even Th9 cells, and then reduced the susceptibility to allergic diseases in offspring." (PMID 30140427, 2018). "The association of TLR2 and TLR4 with allergies is in line with previous studies, so we cannot exclude such influences on the modulation of TLRs in ERM severity." (PMID 39062973, 2024). "In the context of allergy treatment, the immune-modulating effects of all three dual TLR2/7 ligands on mast cells are of special interest, since they constitute evidence of potentially important safety features." (PMID 29204451, 2017). "At the molecular level, activation of the TLR2/4 pathways has been shown to upregulate Tregs and induce cytokine secretion in both children and animal models with allergy development." (PMID 27646403, 2016). "In farmers' families, LPS exposure and higher levels of TLR2 mRNA were related to lower incidence of allergic diseases." (PMID 25973430, 2015). "The contribution of TLR4 to the DP-induced mechanism is essential in allergic diseases, and TLR2 is activated by DP in alveolar macrophages, which is independent or dependent on TLR4." (PMID 25243400, 2014). "Moreover, TLR2, 6, and 9 agonists given before allergen challenge markedly inhibited early and late phase reactions of allergic diseases [31, -33]." (PMID 35484967, 2022). "In addition, it has been shown that LSM are a more potent TLR2 stimulus than viable LGG in an allergy mouse model and immunomodulatory effects of LGG have been TLR 2 associated." (PMID 30042761, 2018).
allergic disease (continued). "Gene polymorphisms of TLR2-15607 (rs1898830 GG SNP) and TLR2-16934 (rs4696480 AA SNP), but not TLR4 rs4986790 and CD14 rs2569190, were involved in the protective role of maternal exposure to farming against allergy in the offspring." (PMID 30140427, 2018). "Previous studies have revealed four genetic polymorphisms in human TLR2, TLR4, and CD14, such as TLR2 rs1898830, TLR2 rs4696480, TLR4 rs4986790 and CD14 rs2569190, which play a role in the pathogenic mechanism of allergic diseases and the protection mechanism of maternal exposure to farming." (PMID 30140427, 2018). "Eosinophils represent an important aspect of chronic allergic disease, and TLR2 may have a key relationship to eosinophils in the mucosal environment within the context of allergy and gastrointestinal inflammation." (PMID 25309051, 2014). "Larger epidemiological studies will be needed to be able to test this hypothesis directly and to confirm that helminths modify the development of allergy by modulating the expression levels of TLR2 and SOCS-3." (PMID 18414649, 2008). "Stimulation of the innate immune system through microbial exposure, such as activation of the innate Toll-like-receptor 2 (TLR2), may reduce the development of allergy in childhood." (PMID 16551363, 2006). "Aside from the detection of pathogenic fungi, our data indicate that the link between CHIT1 and the TLR2 sensing system may also be relevant in the context of HDM allergies, where CHIT1-generated chitin oligomers could serve as TLR2-acting adjuvants for HDM antigens." (PMID 40098951, 2025). "These properties suggest that TLR2/6 ligands may have utility in the treatment of allergies." (PMID 29204451, 2017). "Because deficiency in Tregs is more obvious in the TLR2-mediated innate immune response pathway, we could seek possible micro-stimulation to up-regulate Tregs in the TLR2 pathway and provide early prevention for allergic diseases in children with maternal allergic histories." (PMID 27646403, 2016). "Finally, a dedicated comparison between TLR2 activation in the small and large intestine and the subsequent Treg and B cell responses would be extremely important for understanding the implications of TLR2 in food tolerance and allergy." (PMID 25309051, 2014). "If TLR2 expression is merely the result of exposure to pathogens, and low SOCS-3 expression is associated with protection from allergy, it would be of interest to know whether SOCS-3 is also lower in the European farmers' environment despite a higher TLR2 expression." (PMID 18414649, 2008). "Therefore, TLR2 agonists may provide potent new strategies either for prevention or treatment of allergies and allergic asthma." (PMID 18315836, 2008). "In line with this hypothesis, it has been shown that children of farmers, known to have a decreased risk of developing allergies, expressed higher levels of TLR2 mRNA in blood compared to children of non-farmers." (PMID 16146574, 2005). "The contribution of activation of innate immunity via TLR4 and TLR2 signaling by microbial compounds comprised in HDM, such as LPS and β-glucans, to initiate Th2 polarization and HDM allergy was clearly confirmed." (PMID 33803079, 2021). "Several studies demonstrated the relationship between TLR2 and TLR4 signaling and the induction of Th1 or suppression of Th2 responses in allergic diseases." (PMID 29467764, 2018). "When the children of this study were divided into those with or without allergies, regardless of maternal allergy status, down-regulation of Tregs according to the TLR2/4 pathway at the newborn stage partly predicted the children’s allergic status." (PMID 27646403, 2016). "The results of the present study have revealed that maternal allergy status has a significant impact on Treg differentiation in the TLR2/4 immune pathway, yet not in the unstimulated pathway." (PMID 27646403, 2016).
allergic disease (continued). "Anyway, the logistic regression analyses suggested that the effects of probiotic supplementation on TLR2 responsiveness were independent of allergy development in this study." (PMID 25002964, 2014). "Another study demonstrated increased production of tumor necrosis factor-alpha and interleukin-1 in cord blood mononuclear cells upon TLR2, TLR4, and TLR5 activation in newborns who later develop allergic diseases, suggesting a link between heightened perinatal TLR response and allergy development." (PMID 21912563, 2012). "Detection of CSGG by Toll-like receptor 2 (TLR2) on dendritic cells is critical for inducing Treg cell induction, suggesting that CSGG can suppress intestinal inflammation and may serve as a therapeutic agent for immune homeostasis and allergic diseases." (PMID 40016142, 2025). "In infants without allergies, the phase pair abundance of Ruminococcaceae was negatively correlated with IL-6 and TNF-α induced by Toll-like receptor-2 (TLR-2), and the lower relative abundance of Ruminococcaceae appeared to be related to food sensitization." (PMID 35911834, 2022). "In light of the studies reviewed above and the results presented in this study, we hypothesize that the dual TLR2/7 ligands CL413 and CL531, but not CL401, hold potential as adjuvants for the treatment of Th2-mediated allergic diseases." (PMID 29204451, 2017).